CCL22 (C-C motif chemokine ligand 22)
Diseases named in the same sentence as CCL22 in open-access papers (continued):
Sharing a sentence is not in itself a finding about the gene and the disease.
COVID-19 (continued). "Taking into consideration the fact that MDC/CCL22 concentrations drop in COVID-19, a hyperinflammatory profile and inadequate reaction to external stimuli may become potential problems in immunity formation." (PMID 37685890, 2023). "Although there are significant differences in terms of age, co-morbidities, and blood parameters, multivariate analysis still showed that the expression of MPO, ADA, CCL22, TNFα, and IL-6 mRNA in nasopharyngeal specimens is higher in COVID-19 patients when compared with the control group." (PMID 36482706, 2023). "However, our study shows that despite such variation, significant difference in CCL22 mRNA expression was still observed between patients with mild and severe COVID-19 in multivariate analysis." (PMID 36482706, 2023). "We believe that the decrease in MDC/CCL22 in COVID-19 patients’ plasma is note-worthy." (PMID 37685890, 2023). "Notably, the concentration of one of the chemokines (CCL22/MDC) was lower in patients with acute COVID-19 than in healthy donors." (PMID 36012323, 2022). "In addition, reduction of CCL22 mRNA expression has been consistently observed in specimens taken on different occasions, with several specimens taken at least 1 month from diagnosis of COVID-19." (PMID 36482706, 2023). "Therefore, reduced expression of CCL22 mRNA in respiratory specimens may suggest impairment of recruitment of dendritic cells in severe COVID-19 patients." (PMID 36482706, 2023). "The figure shows lower expression levels of CCL22 and CCL17 in high-severity COVID-19 samples compared to mild and moderate samples." (PMID 40362649, 2025). "CCL-22 and CXCL-17, which are often raised alongside CCL-19 in COVID-19, showed little difference between the two arms." (PMID 39000027, 2024). "CCL-19, CCL-22, and CXCL-17 are also frequently raised in acute COVID-19 cases and are involved in T-cell, dendritic cell, and macrophage chemotaxis." (PMID 39000027, 2024). "CCL22, IL-12/IL-23p40, IL-5, IL-17A and TNF-β levels, on the other hand, were greater in mild or moderate COVID-19 patients than in severe COVID-19 patients (P < 0.05)." (PMID 35958594, 2022). "Our findings reveal that CRP, SAA, VCAM-1, CXCL10, CCL22 and IL-10 levels are promising biomarkers for COVID-19 disease severity, suggesting that plasma inflammatory mediators could be used as warning indicators of COVID-19 severity, aid in COVID-19 prognosis and treatment." (PMID 35958594, 2022). "In contrast, CCL22, CCL28, and Fms-related tyrosine kinase 3 ligand (Flt3L) were positively correlated with basophil frequency, particularly in COVID-19 patients with moderate disease." (PMID 34548411, 2021). "Comparison of the MPO, ADA, CCL22, TNFα, and IL-6 mRNA expression between patients with and without completion of COVID-19 vaccines did not reveal any statistically significant differences." (PMID 36482706, 2023). "Antibodies to the three chemokines with P < 10−4 (CCL19, CCL22 and CXCL17) clustered together and by themselves were sufficient to correctly assign healthy controls and COVID-19 convalescents with high accuracy (96.8%), so they were defined as a ‘COVID-19 signature’." (PMID 36879067, 2023). "However, in the case of COVID-19, the opposite trend is witnessed as MDC/CCL22 levels decrease." (PMID 37685890, 2023).
lymphoma (14 papers, 2015 to 2024). A malignant (clonal) proliferation of B- lymphocytes or T- lymphocytes which involves the lymph nodes, bone marrow and/or extranodal sites. "Of Note, the effect of downregulated CCL17/TARC and CCL22 was even detectable when the analysis was restricted to EBV+ lymphomas." (PMID 38836098, 2024). "Several studies have demonstrated CCL22 involvement in maintaining a suppressive tumor microenvironment, and the development and progression of cancer, including lymphoma." (PMID 36982699, 2023). "RNA-seq analysis also revealed that several different T-cell chemokines (including CCL5, CCL20, and CCL22) are over-expressed in the Δ3C virus-infected, versus WT virus-infected, lymphomas, a finding confirmed by qPCR analysis of tumor cell-derived cDNA." (PMID 30125329, 2018). "In accordance with this finding, Toulza and colleagues have previously demonstrated that the concentration of CCL22 in adult T-cell leukemia/lymphoma patients was abnormally high and correlated with the frequency of CD4+FoxP3+ cells." (PMID 26020249, 2015). "Therefore, consistent with previous studies, CCL17 and CCL22 expression appears to be exclusive to cHL primary tumor cells and cell lines and likely represents a specific feature of this lymphoma over ALCL." (PMID 31581676, 2019). "In CTCL, extravasation of lymphoma cells into the skin is mediated by CCL17 and CCL22 released from epidermal cells." (PMID 29915722, 2018). "Since EBV+ lymphomas secrete high quantities of CCL3, CCL4, CCL22, and CXCL10 compared to EBV- lymphoma lines, the high expression of CCR5, CCR4, and CXCR3 on both EBV VST groups may indicate complementary/alternate axes of migratory mechanisms." (PMID 39011042, 2024). "Treg have been shown to be recruited to the TME via C-C motif chemokine ligand 17 (CCL17) and C-C motif chemokine ligand 22 (CCL22; herein described together as CCL17/22) that are expressed directly by some lymphomas or by infiltrating immune cells within the TME." (PMID 35025968, 2022). "In addition, LOAd703-infected lymphoma cells upregulated the secretion of several chemokines (CXCL10, CCL17, CCL22, CCL3, CCL4) essential for immune cell homing, leading to enhanced CAR T-cell migration." (PMID 33666760, 2021). "We also attempted to stain for the presence of CCL22 in tumor tissue but were not able to establish a satisfactory staining protocol, which was based on previous work on lymphoma tissue." (PMID 28481241, 2017).
allergic asthma (13 papers, 2015 to 2025). A asthma with a basis in a pathological type I hypersensitivity reaction. "In contrast, children born with lower CCL22 levels appear to be inversely associated with the risk of allergic asthma later in life." (PMID 29662241, 2018). "CD11b+ DCs are primary sources of type 2 chemokines CCL17 and CCL22, which recruit Th2 cells to the airways in allergic asthma, thus contributing to Th2 inflammation." (PMID 40405264, 2025). "CCL22 is considered to be upregulated in the lungs of patients with allergic asthma and in skin lesions during dermatitis." (PMID 32760393, 2020). "Indeed, the CCL22-neutralizing decoy molecule GPN136 was able to successfully decrease the level of lung inflammation in an experimental in vivo model of allergic asthma." (PMID 34177944, 2021). "Also, we recommend selective suppression of pathogenic M2a proteins e.g. TGM2, CCL17/CCL22, TGF-β1, and murine Arg1, FIZZ1 and CHI3L3, for the future developments of effective therapies for allergic asthma." (PMID 32024540, 2020). "Also, CCL17 and CCL22 induce naïve T cell differentiation into Th2 cells, indicating the pathogenic role of CCL17 and CCL22 in allergic asthma." (PMID 32024540, 2020). "In conclusion, the data from this study demonstrate for the first time that compound 8a as a small molecule antagonist specifically targeting CCR4/CCL17/CCL22/CKLF1 axes effectively attenuates the allergic airways inflammation in a murine model of allergic asthma in vivo." (PMID 29118379, 2017). "The production of chemokines, particularly CCL22, plays a crucial role in regulating the migration of CC chemokine receptor 4 (CCR4)‐expressing immune cells to the airways in type 2 inflammatory airway disorders, such as allergic asthma." (PMID 39508721, 2024). "More importantly, accumulating evidence reveals that in allergic asthma, M2 macrophages release high levels of chemokines, including CCL-17 and CCL-22, resulting in the recruitment of Th2 cells and amplification of polarized Th2 cell responses in the bronchial tissue." (PMID 37957139, 2023). "Since CCL17 and CCL22 are involved in the pathogenesis of atopic diseases, we finally studied the in vivo activity of GPN279 and GPN136 at inhibiting inflammatory cell recruitment in a mouse model of allergic asthma." (PMID 26442456, 2015).
ovarian tumors (13 papers, 2008 to 2025). "Tregs (CD25+CD127-) are recruited to ovarian tumors/ascites via CCL22 and are associated with inferior survival, suggesting an immunologic barrier to chemotherapy response." (PMID 41415287, 2025). "Tregs migrate into ovarian tumors, which is believed to be due to the action of C-C motif chemokine 22 (CCL22) in the tumor microenvironment." (PMID 36428581, 2022). "Blockade of CCL22 has been demonstrated to reduce Tregs infiltration into ovarian tumors and induce tumor rejection in a murine xenograft model." (PMID 28472762, 2017). "Blockade of CCL22-CCR4 interaction by monoclonal antibodies to CCL22 significantly reduced Treg migration to ovarian tumors in experimental models." (PMID 28415693, 2017). "Ovarian tumor macrophages upregulate and secrete the chemokine CCL22 which promotes T regulatory cell (Treg) trafficking to the tumor." (PMID 25806106, 2015). "In mice bearing primary human ovarian tumors, treatment with an anti-CCL22 mAb decreased Treg migration into tumors." (PMID 25806106, 2015). "Regulatory T cells (Treg) are recruited to ovarian tumors by the chemokine CCL22 (which is highly expressed by ovarian tumors), and the presence of Treg confers immune privilege and is associated with a poor prognosis and increased mortality." (PMID 26343197, 2015). "Similarly, TAMs in ovarian tumors and ascites produce abundant CCL22, attracting Tregs and suppressing immune surveillance, whereas CCL22 inhibitors reduce T cell migration." (PMID 40703514, 2025). "The CCL28 and CCL22/CCL17–CCR4 signaling axes selectively recruit Tregs into ovarian tumors." (PMID 40703514, 2025). "In addition to CCL22 expression, ovarian tumor macrophages express another receptor with immunosuppressive properties, B7-H4." (PMID 25806106, 2015). "Our results suggest that macrophage-derived chemokine, CCL22, may be produced locally by ovarian tumor cells." (PMID 25647263, 2015).
cervical carcinoma (12 papers, 2017 to 2024). A carcinoma arising from either the exocervical squamous epithelium or the endocervical glandular epithelium. "Higher infiltration rates of CCL22+ cells are reported to be associated with poor outcomes in cervical cancer patients." (PMID 36146599, 2022). "CCL22+-infiltrating cells are thought to be significantly associated with the prognosis of cervical cancer patients." (PMID 35805111, 2022). "Our study demonstrates that high CCL22(+) infiltrating cells particularly M2-like macrophage cells, is associated with a poor outcome of cervical cancer patients." (PMID 31842422, 2019). "In addition, our own studies showed that high CCL22(+)-infiltrating cells, particularly M2-like macrophages, are associated with a poor outcome of cervical cancer patients." (PMID 37894319, 2023). "However, the association of CCL22 from cervical cancer cells or macrophages and regulatory T cells is still elusive." (PMID 31842422, 2019). "In conclusion, our findings suggest that the increase in CCL22 (+) infiltrating M2-like macrophage cells may recruit more T-regs in CC tissue and cause a poor prognosis for cervical cancer patients." (PMID 31842422, 2019). "In addition, we have demonstrated that CCL22 is associated with cervical cancer prognosis." (PMID 35805111, 2022). "Patients with cervical cancer and elevated CCL22+ infiltrating cells require more aggressive treatment." (PMID 39513112, 2024). "The CCL22 mRNA level in a local immune microenvironment of normal cervix tissue was lower than that in cervical cancer tissue." (PMID 35805111, 2022). "To ascertain CCL22 mRNA level in vitro in cervical cancer, we quantified its expression in TAMs, M1, M2a, M2b, and M2c macrophages." (PMID 35805111, 2022). "Previously, by performing a tissue microarray (TMA) using immunohistochemistry (IHC) and double immunofluorescence, we have proved that CCL22 is mainly secreted by infiltrating macrophages and less so by cervical cancer cells in cervical tumor tissue." (PMID 35805111, 2022). "The results of our study show that cervical cancer patients with elevated CCL22 + infiltrating cells need more aggressive treatment." (PMID 34833360, 2021). "CCL22 is produced by tumor-associated macrophages (TAM) and DC in CRC and PDAC, cervical carcinoma, HNSCC and ovarian carcinoma." (PMID 33924428, 2021). "A spearman correlation analysis indicated that both the number of CCL22+ cells and the CCL22 expression in cervical cancer cells were positively correlated with that of FOXP3+ cells (r = 0.210, p = 0.002; r = 0.144, p = 0.027, respectively)." (PMID 31842422, 2019). "This study revealed a similar trend, that the protein level of CCL22 from both cervical cancer cells and infiltrating cells was positively correlated with FOXP3." (PMID 31842422, 2019). "The present study determined the functional role of CCL22 in infiltrating macrophages in cervical cancer." (PMID 31842422, 2019). "We postulated that the number of CCL22+ cells or the CCL22 expression in cervical cancer cells is correlated to the number of FOXP3+ cells in cervical cancer specimens." (PMID 31842422, 2019). "The IRS of CCL22 expressed in cervical cancer cells was evaluated and the number of CCL22+ and FOXP3+ cells was counted." (PMID 31842422, 2019). "This study is the first to report the relationship between CCL22 expression and the prognosis of cervical cancer (CC) patients." (PMID 31842422, 2019). "The group with a higher number of CCL22+ infiltrating cells shows a lower overall survival rate (OS) than that of the group of lower number of CCL22+ infiltrating cells in cervical cancer." (PMID 31842422, 2019). "The findings of our study indicate that cervical cancer patients with elevated CCL22+ infiltrating cells require more aggressive treatment." (PMID 31842422, 2019). "This correlation was defined by calculating the IRS of CCL22 expression in cervical cancer cells and counting the number of CCL22+ and FOXP3+ cells." (PMID 31842422, 2019).
cervical carcinoma (continued). "In cervical cancer, the CCL22 mRNA levels of neoplastic foci and tumor periphery is positively correlated with FOXP3." (PMID 31842422, 2019). "The correlation analysis indicated that in immune microenvironment of cervical cancer, the mRNA level of CCL22 and CCR4 was strengthened as the Foxp3 mRNA level increased and vice verse." (PMID 28086903, 2017). "Besides, the mRNA level of CCL22 in cervical cancer cell lines alone or co-cultured with M0 macrophages were extremely low." (PMID 35805111, 2022). "A higher amount of infiltrating CCL22+ cells predicts a poor prognosis in cervical cancer." (PMID 35805111, 2022). "In conclusion, our study revealed that CCL22 could be a therapeutic target for cervical cancer, which might be because of its role in regulating macrophage polarization." (PMID 35805111, 2022). "For cervical cancer, our group could identify TAMs as a major source of CCL22, a chemokine responsible for Treg cell infiltration." (PMID 35563052, 2022). "Moreover, the mRNA of CCL22 is expressed higher in cervical cancer tissue than that which is present in normal cervical tissue." (PMID 35805111, 2022). "However, regarding our study, further studies need to be performed to show the effects of M2a macrophages on cervical cancer cells after knocking down CCL22." (PMID 35805111, 2022). "In this study, we assessed the effect of CCL22 on the expression of M2a marker CD206 by flowcytometry and revealed that CCL22 could be a therapeutic target for cervical cancer, which might be due to its role in regulating macrophage polarization." (PMID 35805111, 2022). "CCL22 was mainly expressed in M2-like macrophages in CC and induced by cervical cancer cells." (PMID 34833360, 2021). "The results showed that the addition of cervical cancer cell supernatant during the differentiation of monocytes into macrophages inhibited the expression of M1 cytokines such as IL‐1β and IL‐6 and promoted M2 cytokines such as IL‐10 and CCL22 expression." (PMID 31943744, 2020). "CCL22 expression is positively correlated with FoxP3 expression in cervical cancer." (PMID 31842422, 2019). "However, further studies need to be performed to show the effect of cervical cancer cells on M2 macrophages and the regulatory mechanisms of CCL22 needs to be studied in the future." (PMID 31842422, 2019). "CCL22 was primarily expressed in M2-like macrophages in CC and induced by cervical cancer cells." (PMID 31842422, 2019). "CCL22 could be a prognostic predictor and therapeutic target to identify and treat cervical cancer patients with poorer clinical outcomes." (PMID 31842422, 2019). "By performing a tissue microarray (TMA) using immunohistochemistry (IHC), we showed that CCL22 could be secreted by cervical cancer cells." (PMID 31842422, 2019). "Cervical cancer (CC) is an important public health problem for women, gene expression patterns which were governed by epigenetic modifications can result in CC, CC-chemokine receptor 4 (CCR4) interacts with C-C-motif ligand 22 (CCL22) is associated with tumor progression or metastasis." (PMID 39513112, 2024). "CCL22 expression is positively correlated with FoxP3 expression, could polarize TAMs toward M2a macrophages and may represent a novel prognostic marker and therapeutic target for the treatment of cervical cancer." (PMID 37894319, 2023). "CCL22 could polarize TAMs toward M2a macrophages in cervical cancer." (PMID 35805111, 2022). "However, by performing flowcytometry, we are the first to show that knocking down CCL22 significantly decreased the MFI of CD206 in TAMs of cervical cancer compared with the control group, which indicated that CCL22 could polarize TAMs to M2a macrophages." (PMID 35805111, 2022). "Therefore, both cervical cancer cell-derived and infiltrating cell-derived cells might recruit T-regs, and the role of CCL22 from infiltrating cells was found to be more significant than that of CCL22 from cervical cancer cells." (PMID 31842422, 2019).